TLE3 (TLE family member 3, transcriptional corepressor)
Diseases named in the same sentence as TLE3 in open-access papers (continued):
Sharing a sentence is not in itself a finding about the gene and the disease.
prostate (1 paper, 2019). "TLE3 was shown to co-localize with FOXA1 and AR at enhancer elements, which are selectively activated during prostate tumorigenesis, underscoring the importance of these transcription factors in this context." (PMID 31855178, 2019).
TLE3 also shares sentences with these, for which no sentence is quoted: colon cancer (3 papers); gastric cancer (3); pancreatic cancer (3); Anxiety (2); diabetes (2); acute myeloid leukemia (1); Alzheimer disease (1); amyloid (1); Arthritis (1); cardiovascular diseases (1); cognitive deficits (1); colorectal tumors (1); dermatitis (1); hepatocellular carcinoma (1); Huntington disease (1); leukemia (1); liver cancer (1); lung adenocarcinoma (1); lymphocytic leukemia (1); lymphopenia (1); malignant meningiomas (1); metabolic disorders (1); nephritis (1); neuritis (1); neuroblastoma (1); pancreatic adenocarcinoma (1); pneumonia (1); psoriasis (1); rectal tumors (1); rhabdomyosarcoma (1).
A further 3 diseases each share a sentence with TLE3 in 1 paper.